ENO1 (enolase 1)
Diseases named in the same sentence as ENO1 in open-access papers (continued):
Sharing a sentence is not in itself a finding about the gene and the disease.
tumor (continued). "Relevant researches have shown that ENO1 is highly expressed in varieties of tumors types and is involved in tumor angiogenesis, invasion, and metastasis." (PMID 35251177, 2022). "It was unexpected that the proteins such as Hsp90ab1, Eno1, Eef2, and vinculin were enriched in the secretome since they are considered tumor promoters intracellularly 35-38." (PMID 35547745, 2022). "ENO1 is involved in proliferative invasion, tumor metastasis and progression in LUAD through glycolysis and the PI3K/Akt pathway." (PMID 35918384, 2022). "Together, these data suggest that ENO1 can affect tumor progression by mediating the PI3K/AKT oncogenic pathway and EMT development." (PMID 35434271, 2022). "The current research on the function of ENO1 in tumor is primarily focused on its effects in glycolysis, while comprehensive analysis of ENO1 in BLCA is less studied." (PMID 35836227, 2022). "Subsequently, a xenograft tumor model was constructed, and the growth of xenograft tumors was significantly inhibited by the downregulation of ENO1 in the LV-FAM126A group." (PMID 35513377, 2022). "Increased urinary ENO1 concentrations in the PCa2 group suggest increased expression of this glycolytic protein in tumor cells." (PMID 35886909, 2022). "Although ENO1 is regarded as an emerging tumor biomarker and oncotherapeutic target, the specific mechanisms of how ENO1 regulates tumor progression have not yet been comprehensively determined." (PMID 35434271, 2022). "We analyzed the expression of ENO1 in four cell lines—two derived from the primary tumor (A375 and WM1341D), and two from lymph node metastases (Hs294T and WM9)." (PMID 35204345, 2022). "Tumor cells in this subgroup express various metabolic regulatory molecules, such as α-enolase 1 (ENO1), LDHA, TPI1, and PGK17." (PMID 36476328, 2022). "In ENO1-silenced tumor cell lines, the glycolysis rate diminishes in favor of the oxidative phosphorylation, but glucose influx remains high." (PMID 35204345, 2022). "In head and neck cancer, mRNA expression of ENO1 was increased in 68% of tumor specimens when compared with their normal counterpart." (PMID 35434271, 2022). "In multiple malignancies, the expression of α-enolase (ENO1) is related to the progression and metastasis of the tumor." (PMID 36712886, 2022). "At the cell surface, ENO1 acts as a plasminogen receptor and is involved in angiogenesis, tumor cell invasion and migration." (PMID 35886909, 2022). "The high expression of glycolytic enzyme alpha-enolase (ENO1), a key biomarker in tumor glycolytic metabolism, dramatically promoted cell growth and migration in A549 cells by activating the FAK/PI3K/AKT signaling pathway." (PMID 36532721, 2022). "The binding of CCDC65 to the oncogenic factor ENO1 stimulates tumour pathogenesis and promotes ubiquitylation and degradation of ENO1 through the recruiting of E3 ubiquitin ligase FBXW7." (PMID 36615513, 2022). "To assess the potential mechanism of the tumor-suppressive action of Eno1, we conducted an immunoprecipitation assay." (PMID 35547745, 2022). "The tumor volume in ENO1-KD with 5-FU group was significantly decreased compared with that in the NC with 5-FU group." (PMID 36620599, 2022). "Ping and colleagues review the relationship between ENO1 and multiple cancer types, evaluate ENO1's potential role in tumor development, and update recent advancements in ENO1-targeted onco-therapies." (PMID 35434271, 2022). "The glycolytic enzyme, α-Enolase (ENO1), catalyzes the production of phosphoenolpyruvate from 2-phosphoglycerate, thereby enhancing glycolysis and contributing to tumor progression." (PMID 35925486, 2022). "The results disclosed that ENO1 expression was remarkably correlated with tumor grade and T stage at both mRNA level and protein level." (PMID 35836227, 2022). "circ-ENO1 acted as a ceRNA to interact with miR-22-3p, and an upregulated ENO1 expression promoted glycolysis and tumor progression in LUAC." (PMID 36338714, 2022).
tumor (continued). "Overexpression of ENO1 in tumor cells significantly correlated with shorter cancer-specific overall survival (p = 0.023) and disease-free survival (p = 0.001)." (PMID 35204345, 2022). "The same study found that the silencing of ENO1, using an anti-ENO1 monoclonal antibody in immunosuppressed mice, inhibited both the tumour growth and the migration and invasion capacity of Panc-1/M cells." (PMID 35204653, 2022). "It has been reported that knockdown of ENO1 expression can inhibit the proliferation and metastasis of tumor cells by inhibiting the phosphorylation/activation of the PI3K/ AKT pathway." (PMID 35513377, 2022). "These outcomes further proved that ENO1 expression was upregulated in BLCA patients and increased ENO1 expression was significantly correlated with tumor malignancy of BLCA." (PMID 35836227, 2022). "combined anti-ENO1 with two other tumor protein biomarkers (carcinoembryonic antigen and cytokeratin 19); consequently, the sensitivity in the diagnosis of the lung was increased to 84%." (PMID 35434271, 2022). "In summary, ENO1 can reduce the tolerance of tumor cells to hypoxia by mediating aerobic glycolysis, thus promoting tumor angiogenesis." (PMID 35434271, 2022). "For example, ENO1 was overexpressed in gastric cancer and functioned as a potential carcinogen to promote tumor progression." (PMID 35836227, 2022). "ENO1, one of the critical enzymes in the glycolytic pathway, is a multifunctional protein with oncogenic properties: it promotes tumor cell proliferation, migration, and invasion, which result in the accelerated progression of various tumors." (PMID 35434271, 2022). "Tumor weight in the ENO1-KD with 5-FU group was the lowest, followed by that in the NC with 5-FU group, and the weight in ENO1-KD group was lower than that in the NC group." (PMID 36620599, 2022). "In SKCM cells, ENO1 overexpression promoted invasion, migration, and proliferation of tumor cells; increased pyruvate and lactate production; and increased β-catenin, MMP-9, MMP-13, and c-Myc levels." (PMID 35925486, 2022). "Application of this approach to deliver cancer vaccine candidates, e.g., enolase-1, was shown to suppress tumor development in mouse models." (PMID 35214706, 2022). "Whole-genome proteomics predicted enolase 1 (Eno1), Hsp90ab1, Eef2, and vinculin as extracellular tumor suppressors." (PMID 35547745, 2022). "Overexpression of ENO1 in tumor cells from patients was correlated with unfavorable prognosticators such as Breslow thickness, Clark level, mitotic activity, and the presence of ulceration." (PMID 35204345, 2022). "The downregulated lncRNA-6195 in HBV-related HCC is a tumor suppressor that binds to the substrate-binding site (aa 237–405) of ENO1 to inhibit tumor growth." (PMID 36203765, 2022). "To assess the potential involvement of the Eno1-CD44 axis in the tumor-suppressive action of Eno1, we conducted an immunoprecipitation assay." (PMID 34373756, 2021). "Nonetheless, despite HEX’s modest permeability across cell membranes, consistent with our previous data, we observed strong inhibition of intracranial tumor growth in mice bearing ENO1-deleted intracranial gliomas." (PMID 34172075, 2021). "Enolase 1 (ENO1), known as coding enolization enzyme 1, played a key role in glucose metabolism and tumor development." (PMID 34544452, 2021). "When patients were categorized by histological tumor subtype, ENO1 was expressed in tumor cells in 76.9% of ESCC cases and in 81.5% in EAC cases, and in matched normal tissues in 7.8% and 11.1%, respectively." (PMID 33628097, 2021). "We have previously shown that iTSC CM, derived from tumor cells, is enriched with atypical tumor-suppressing proteins, including Hsp90ab1, Eno1, and Ubc." (PMID 34830748, 2021). "Although ENO1 has been extensively evaluated using proteomics and IHC in tumor cell lines and tissues, few studies have examined circulating levels of the enzyme in cancer patients." (PMID 33628097, 2021).
tumor (continued). "We used ENO1 shRNA to downregulate the expression of ENO1, and the tumor was isolated for measurements at indicated times." (PMID 33968941, 2021). "Three atypical tumor-suppressing proteins, Hsp90ab1, Eno1, and Ubc, focused in this study, are moonlighting proteins with contrasting roles in the intracellular and extracellular domains." (PMID 34830748, 2021). "This study found that ENO1 in EC cells was mainly localized in the cytoplasm, consistent with its supporting role in the high metabolic rate of tumor cells." (PMID 33628097, 2021). "Alpha-enolase (ENO1) worked as an enzyme that had a pivotal role in glycolysis, particularly in the glycolysis of tumor cells." (PMID 34504528, 2021). "Taken together, multiple lines of evidence supported the anti-tumor action of Eno1 and Ubc in iTS CM." (PMID 34373756, 2021). "Citrullinated ENO1 epitope can be used to generate strong Th1 responses that can preferentially target tumor cells." (PMID 34671213, 2021). "The comparison of expressions of LDHA, GAPDH, and ENO1 showed overall higher expression in tumor samples as compared to the normal samples." (PMID 34831287, 2021). "Recent studies reported that ENO1 was correlated with cancer differentiation and progression in several tumor types by interacting with lncRNAs." (PMID 34627260, 2021). "Herein our study indicates that ENO1 of tumor cells can also be regulated by neutrophils in the BC microenvironment." (PMID 34312368, 2021). "Echoing the role of surface ENO1 (sENO1) in cancer cell invasiveness, vaccination of the mice with ENO1 has been reported to elicit anti-tumor immune responses, thereby delaying tumor progression and extending survival." (PMID 34136381, 2021). "Although alterations of several genes (such as Hebp1, Eno1, and Taf9) other than Ankrd52 are more frequently detected in our tumor profiling, their targeting sgRNAs exhibited much less enrichment or fold-change as compared to those of Ankrd52." (PMID 34853298, 2021). "They show that citrullinated epitopes from ENO1 can be used in vaccines to induce potent CD4+ T cell responding to an anti-tumor effect with minimal cross reactivity to healthy tissue." (PMID 34671213, 2021). "Following the previous result, overexpression of ENO1 resulted in larger tumor sizes, suggesting that ENO1 was an oncogene." (PMID 33968941, 2021). "These tumor-derived iTS cells secreted anti-tumor factors such as Eno1 and Ubc in their CM and eliminate neighboring tumor cells." (PMID 34373756, 2021). "ENO-1 is a glycolytic enzyme which has been found to play other roles in inflammation, tumor suppression and monocyte and mast cell differentiation." (PMID 34451426, 2021). "ENO-1 has been found to play other roles in inflammation, tumor suppression and monocyte and mast cell differentiation." (PMID 34451426, 2021). "As a potential anti-tumor mechanism of BML284-treated osteoclast-derived CM (BM CM), we examined the role of three atypical tumor-suppressing proteins: Hsp90ab1, enolase 1 (Eno1), and polyubiquitin C (Ubc)." (PMID 34830748, 2021). "Immunoprecipitation revealed that Hsp90ab1 and Eno1 interact and inhibit the progression of tumor cells by blocking TGFβ activation and interacting with CD44, a cell-adhesion receptor." (PMID 34830748, 2021). "We also performed an immunoprecipitation assay to elucidate the mechanism of Eno1's anti-tumor action." (PMID 34373756, 2021). "Enolase, specifically isoform 1 (ENO1), has been reported as a critical regulator in tumor formation since the silencing of ENO1 has implications in the adaptation of autophagy and catabolic pathways, which affects the growth of tumors, inducing senescence." (PMID 33809480, 2021).
tumor (continued). "As a plasminogen receptor, ENO1 converts plasminogen to plasmin, which involves in the metastatic spread of cancer from the primary tumor to a remote site." (PMID 34671213, 2021). "Studies investigated the regulatory mechanism circ-ENO1 on its host gene ENO1 and its function in glycolysis and tumor progression." (PMID 34489401, 2021). "For example, a previous study revealed that circRNA-ENO1 played a crucial role in glycolysis and tumor progression of LUAD by promoting the expression of its host gene ENO1." (PMID 34539783, 2021). "ENO1 also strengthens the infiltration ability of monocytes and macrophages, and it can participate in tumor formation by controlling the expression of the c-myc oncoprotein through the Notch signaling pathway." (PMID 33628097, 2021). "Whole-genome proteomics analysis revealed that a pair of unexpected proteins, enolase 1 (Eno1) and Ubc, were enriched in CM and they acted as remarkable tumor suppressors in the extracellular domain." (PMID 34373756, 2021). "The results thus indicated that Hsp90ab1, Eno1, and Ubc were involved in the anti-tumor actions of BM CM." (PMID 34830748, 2021). "Results from immunohistochemistry showed that ENO1 protein was upregulated in tumor tissue and levels of ENO1 was also upregulated in late-stage CRC." (PMID 34035230, 2021). "As the activation of Wnt signaling is paradoxical for the therapeutic strategy, so as the predicted tumor suppressors such as Eno1 and Ubc are." (PMID 34373756, 2021). "Both POMHEX and HEX exerted dramatic antineoplastic effects on ENO1-deleted tumor cells in culture and in ENO1-deleted xenograft tumors." (PMID 34172075, 2021). "ENO1 overexpression has been correlated with tumor progression and/or worse prognosis in several solid malignancies." (PMID 33628097, 2021). "Otherwise, circulating ENO1 can be degraded by some activated proteases secreted from tumor or released from tumor cell death." (PMID 33628097, 2021). "ENO1 has been identified to be involved in the process of drug resistance in many types of tumor cells." (PMID 34544452, 2021). "And we also found that the higher level of methylation of ENO1’s promoter in normal group than tumor group." (PMID 33968941, 2021). "Some studies have reported that lncRNAs or proteins can interact with ENO1 and affect its expression or activity in tumours." (PMID 31957179, 2020). "ENO1 specific T cells from peripheral blood to tumor are inhibited by a number of immunosuppressive mechanisms." (PMID 33643901, 2020). "Previous studies have reported the effects of ENO1 on tumor development, which support our results showing that ENO1 is significantly correlated with prognosis, tumor stage, and immune infiltrates in cancers." (PMID 33643901, 2020). "This mini-review summarizes our current knowledge of ENO1 functions in cancer and its growing potential as a cancer biomarker and guide for the development of novel anti-tumor treatments." (PMID 33584813, 2020). "This study aimed to investigate the correlation of ENO1 with prognosis, tumor stage, and levels of tumor-infiltrating immune cells in multiple cancers." (PMID 33643901, 2020). "Efforts should be directed towards the preparation of prospective clinical trials to evaluate the prognostic value of ENO1 as a tumor marker in cancers at different stages." (PMID 33643901, 2020). "More importantly, our co-IP and mass spectrometry data revealed that ENO1 was a downstream target of CD47 in the tumor cells." (PMID 32226539, 2020). "Some studies have shown that ENO1 acts as a potent promoter in tumor cells by regulating AMPK/mTOR and PI3K/AKT signaling and inactivating a downstream signaling pathway." (PMID 33226369, 2020). "In TIMER, after adjustments for tumor purity, the ENO1 expression level was significantly correlated with 14 out of 57 immune cell markers in CESC, 30 out of 57 immune cell markers in KICH, and 24 out of 57 immune cell markers in LUAD." (PMID 33643901, 2020).
tumor (continued). "ENO1 expression and its influence on tumor stage and clinical prognosis were analyzed by UCSC Xena browser, Gene Expression Profiling Interactive Analysis (GEPIA), The Cancer Genome Atlas (TCGA), and GTEx Portal." (PMID 33643901, 2020). "Emerging data indicate that ENO1 silencing inhibits tumor cell proliferation and invasion and reverses EMT progression." (PMID 33184263, 2020). "In particular, ENO1 expressed on the cell surface has been shown to promote migration and metastasis of tumor cells by inducing plasminogen activation and extracellular matrix degradation as a plasminogen receptor." (PMID 33643901, 2020). "ENO1-specific T cells can recirculate from the tumor to the periphery despite different functional profiles." (PMID 33643901, 2020). "The violin plots were generated to demonstrate the impact of ENO1 expression on tumor stage in these cancers." (PMID 33643901, 2020). "To explore the clinical significance of ENO1 in the development of GC, we determined the expression of ENO1 in GCs and their adjacent non-tumorous tissues by IHC." (PMID 33067426, 2020). "Alpha-enolase (ENO1, 47 kD) has recently emerged as a major driver of tumor metabolism and progression and is considered a rising cancer biomarker and therapeutic target." (PMID 33584813, 2020). "Previous studies showed that ENO1 located on the surface in tumour cells is subjected to post‐translational modifications, including acetylation, methylation and phosphorylation." (PMID 32285549, 2020). "For example, in breast cancer, enhanced ENO1 expression correlated with greater tumor size, poor nodal status, and a shorter disease-free interval." (PMID 33584813, 2020). "In the present study, the correlations of ENO1 with prognosis, tumor stage, and immune infiltrating levels in multiple cancers were investigated via analyzing TCGA data." (PMID 33643901, 2020). "Acting as a plasminogen receptor, ENO1 “moonlights” on the surface of tumor cells to facilitate plasminogen conversion into plasmin." (PMID 33584813, 2020). "ENO1, as a key glycolytic enzyme involved in catalysing the conversion of 2‐phospho‐D‐glycerate to phosphoenolpyruvate, can enhance glycolytic process in tumour cells because of the Warburg effect." (PMID 32285549, 2020). "Compared with the minimal fluorescence of CA group, the pseudo green fluorescence of the Al-CA probe was observed in the tumor tissues, which merged partially with ENO1 protein antibody staining (red) and presented a colocalized yellow fluorescence." (PMID 32013122, 2020). "The involvement of ENO1 in a variety of pathways, particularly glycolysis-related pathways, is closely related to tumor formation and progress." (PMID 33643901, 2020). "The relationship between ENO1 expression and tumor immunity was analyzed by Tumor Immune Estimation Resource (TIMER) and GEPIA." (PMID 33643901, 2020). "Overexpressed ENO1 promotes resistance to cisplatin and other anti-tumor drugs in cancer cells by increasing glycolysis and cell proliferation, interaction with microtubules, and cell adhesion." (PMID 33584813, 2020). "TPI1, LDHA, and ENO1 were also found to be frequently upregulated across various tumor types in a prior meta-analysis study." (PMID 32411371, 2020). "As a result, the phosphorylation of PI3K/AKT was also reduced after the suppression of ENO1 phosphorylation, which further inhibited tumor growth and metastasis, leading to a better prognosis of NSCLC." (PMID 32795333, 2020). "ENO1 overexpression in hepatocellular carcinoma increased with tumor de-differentiation and correlated positively with venous invasion." (PMID 33584813, 2020). "ENO1 overexpression in multiple cancer types, localization in the tumor cell surface, and demonstrated targetability make this protein a promising cancer biomarker and therapeutic target." (PMID 33584813, 2020).